APOE (apolipoprotein E)
Diseases named in the same sentence as APOE in open-access papers (continued):
Sharing a sentence is not in itself a finding about the gene and the disease.
atherosclerosis (continued). "Studies have shown that BspA-mediated coaggregation with T. denticola and F. nucleatum exacerbates foam cell formation in THP-1 cells and accelerates atherosclerosis progression in ApoE (−/−) mice." (PMID 40136726, 2025). "CD4+ T cells significantly influence the progression of atherosclerotic plaques, as demonstrated by crossing apoE−/− mice, which are prone to atherosclerosis, with immunodeficient scid/scid mice." (PMID 39940640, 2025). "By studying the aortic transcriptome of atherosclerosis‐prone apolipoprotein E (ApoE−/−) mice, we aimed to identify novel players in the progression of atherosclerosis." (PMID 39835780, 2025). "In patients with T2D and atherosclerosis, vascular expression levels of BDH1 are decreased, which is consistent with decreased BDH1 expression in the aorta from diabetes-induced atherosclerosis and ApoE−/− mice models." (PMID 39198360, 2025). "ApoE−/− mice were fed a high-fat diet (HFD) for eight weeks to expedite atherosclerosis formation, followed by a ten-week treatment with DHL or Simvastatin." (PMID 40537740, 2025). "Autophagy plays a significant role in atherosclerosis progression, as shown by studies on ApoE-null mice with Atg7 deletion in VSMCs." (PMID 40354374, 2025). "Faecalibacterium prausnitzii reduces intestinal LPS synthesis, enhances mechanical and mucosal barriers, decreases plasma LPS levels, and alleviates atherosclerosis in ApoE-/- mice." (PMID 40356907, 2025). "Atherosclerosis is difficult to be detected for most genetically engineered mice, and therefore, these mice are often crossed to ApoE−/− mice to make the detection of the atherosclerotic phenotypes easier." (PMID 40383150, 2025). "Animal studies showed that l‐Arg by inhibiting NET formation can reduced atherosclerosis and arterial thrombosis in ApoE–/– murine." (PMID 40161001, 2025). "Advancements in gene editing techniques, particularly zinc finger nuclease, helped to create more advanced genetic models, which include also models of atherosclerosis, such as APOE, APOC3 and CETP knockout (KO) rabbits." (PMID 39364866, 2025). "PXR deficiency reduces CD36 expression and lipid accumulation in macrophages, thereby attenuating atherosclerosis in ApoE−/− mice." (PMID 41438090, 2025). "One study showed that Z-Ligustilide significantly alleviates atherosclerosis in ApoE-/- mice by reconstructing gut microbiota and maintaining intestinal barrier integrity via cannabinoid receptor 2 activation." (PMID 40356907, 2025). "Previously, CD36‐selective ligands have reduced macrophage accumulation in aortic lesions, diminished foam cell formation, and mitigated atherosclerosis progression in apoE‐null mice." (PMID 39552437, 2024). "Oral administration of Oxy210 formulated in WD at 4 mg/g for 16 weeks showed a significant amelioration of atherosclerosis in APOE*3-Leiden.CETP mice." (PMID 39404395, 2024). "For instance, a previous study showed that endothelial IR- and apolipoprotein E-knockout mice had increased atherosclerosis." (PMID 39195275, 2024). "In this study, we found that diabetic ApoE–/– mice showed aggravated atherosclerosis as hyperglycemia damaged the efferocytosis capacity at least partially due to decreased expression of Mer tyrosine kinase (MerTK) on macrophages." (PMID 38614985, 2024). "Although there was some overlap APOE, widely known for its protective role in atherosclerosis, it is more relevant to LOP." (PMID 37740793, 2024). "Here, to explore the therapeutic potential of Larp7 overexpression in treating atherosclerosis, we induced Larp7 overexpression in a ApoE knockout (ApoEKO) mouse by utilizing Tet‐on system and Cre‐loxp system." (PMID 38818612, 2024).
atherosclerosis (continued). "Atherosclerosis burden was assessed in female ApoE−/− mice with CKD and mice with CKD and PD‐fluid exposure and compared with control mice." (PMID 38979792, 2024). "Liraglutide effect on atherosclerosis was studied on both human atherosclerotic plaque cultures and human peripheral blood macrophages as well as apoE−/− mice on a high-fat, high-cholesterol diet." (PMID 39741663, 2024). "Atherosclerosis was more prominent in the aortic roots and descending aortas of the ApoE KO + HFD group than in those of the ApoE KO + HFD+Met group." (PMID 39223261, 2024). "Accordingly, endothelial deletion of ALK5 or TGFBR2 in the ApoE−/− atherosclerosis mouse model reduces atherosclerosis plaque burden, plaque collagen content, fibronectin deposition and VCAM-1 expression." (PMID 38323651, 2024). "ASA6 is a new human scFv antibody that interacts with oxLDL and blocks atherosclerosis progression in ApoE−/− mice." (PMID 38952543, 2024). "Our study demonstrated that capsaicin effectively reduces systemic inflammation, dyslipidemia, and atherosclerosis development in ApoE KO mice." (PMID 39339767, 2024). "Liver-targeted Angptl4 silencing potently attenuates hyperlipidemia and atherosclerosis development in APOE*3-Leiden.CETP mice, and liver-targeted ANGPTL4 silencing is well tolerated in non-human primates." (PMID 39259836, 2024). "In this study, ApoE-KO mice were used as an in vivo animal model of the formation of atherosclerosis." (PMID 39337364, 2024). "Atherosclerosis is the underlying cause of stroke, and HDL, apoA-I, and endogenous apoE prevent inflammation and oxidative stress and promote cholesterol efflux to reduce atherogenesis." (PMID 39174970, 2024). "In this study, we investigated the possible anti-atherosclerotic effects of imeglimin using atherosclerosis model ApoE KO mice treated with streptozotocin (STZ)." (PMID 38504316, 2024). "Our previous study demonstrated that over‐expression of miR‐30a‐5p mitigated atherosclerosis and improved lipid metabolism in ApoE−/− mice." (PMID 39360667, 2024). "Apigenin (100 mg/kg/day for 42 days) was reported to reduce the size of sclerotic lesions in atherosclerosis-prone apolipoprotein E null mice." (PMID 38629096, 2024). "To explore the role of eIF6 in regulating gut microbiota on atherosclerosis, we constructed a double knockout mouse model, ApoE−/−/eIF6+/− mice." (PMID 39225466, 2024). "Our findings show that giving E. faecium NCIMB11508 orally can inhibit atherosclerosis progression in ApoE−/− mouse models." (PMID 39451408, 2024). "First, there are some important dissimilarities regarding atherosclerosis development between ApoE−/− mice and humans." (PMID 39232217, 2024). "ApoE−/− mice develop accelerated atherosclerosis, with initial lesions being visible as early as 6 weeks of age44." (PMID 39232217, 2024). "Treatment with soluble agonist CTLA-4 Ig fusion protein reduced atherosclerosis progression in hyperlipidemic and hyperhomocysteinemic ApoE−/− mice by competitively inhibiting CD28-CD80/86 co-stimulatory T-cell activation and pro-inflammatory cytokine release." (PMID 39926714, 2024). "Along this line, in the present study, we first reported that oral administration of SAMB significantly ameliorated HFD-induced atherosclerosis in ApoE−/− mice." (PMID 38839811, 2024). "It is generally considered that ApoE protects against the development of atherosclerosis, but this benefit depends on the ApoE isoform, the total plasma ApoE level, and the cell type responsible for the synthesis and secretion of ApoE." (PMID 38429638, 2024).
atherosclerosis (continued). "Similarly, in line with other findings demonstrating atherosclerosis development through prolonged topical application of Pg in the oral cavity, our study revealed that Pg-induced periodontal disease notably increased the lipid deposition in the arterial wall of ApoE-deficient mice." (PMID 38892314, 2024). "In the present study, MO was more potent than FO in preventing atherosclerosis of ApoE−/− mice, which provided a new strategy for nutritional prevention of atherogenesis." (PMID 38410635, 2024). "PPARD has been clearly clarified to be involved in cholesterol metabolism by encoding the lipid‐activated nuclear receptor and activate gene transcription, and deletion of the gene in ApoE knockout mice showed attenuated atherosclerosis." (PMID 39673281, 2024). "In ApoE−/− diabetic mice, pioglitazone was able to suppress the development of atherosclerosis plaques." (PMID 39194749, 2024). "Previous studies have reported that dementia and its two main subtypes, AD and vascular dementia, are both associated with atherosclerosis, with the etiology of AD involving the interaction between ApoE and atherosclerosis." (PMID 39328244, 2024). "For flaxseed oil exhibited anti-atherosclerosis activity on high-fat diet-induced ApoE−/− mice, alloLCA and isoLCA were positively correlated with LPS in plasma, and CDCA and HDCA were positively correlated with TNF-α in aorta." (PMID 39403395, 2024). "ApoE-/- mice had less atherosclerosis and increased survival compared to wild-type and individual FABP-knockout counterparts." (PMID 37794302, 2024). "Knockdown of PSGL-1 in an ApoE-/- mouse model reduced monocyte infiltration and leukocyte adhesion, decreased atherosclerotic plaque area and was protective against atherosclerosis." (PMID 39399488, 2024). "Atherosclerosis-prone ApoE-/- mice fed with a high-cholesterol diet showed increased LDL deposition and greater apoptosis in the common carotid artery region associated with thinner endothelial glycocalyx." (PMID 39728298, 2024). "Using a 1 Tesla small animal MRI scanner, they were able to see atherosclerotic plaques in several aortic areas in atherosclerosis-prone ApoE−/− mice." (PMID 38794614, 2024). "The APOE*3-Leiden.CETP model thus appears to be a relevant model for evaluating the effects of modulation of lipid metabolism on atherosclerosis development." (PMID 38428154, 2024). "This study demonstrated that even a small amount of apoE expression in macrophages and monocytes of hippomorphic apoE mice led to increased miR‐146a levels and inhibited macrophage proinflammatory responses, monocytosis and atherosclerosis in hyperlipidaemia." (PMID 39392102, 2024). "In ApoE−/− mice, Pon1 gene deletion also increased atherosclerosis and oxidative stress, manifested by elevated epitopes in plasma-oxidized phospholipid, biologically active oxidized phospholipids in isolated endogenous intermediate-density lipoprotein/LDL." (PMID 39594433, 2024). "In animal experiments, FDT exerted protective effects against atherosclerosis by reducing the plaque area and lipid levels in ApoE−/− mice." (PMID 38794213, 2024). "In this study we utilised the high fat fed Apolipoprotein E knockout mouse (ApoE−/−) model of atherosclerosis." (PMID 39276419, 2024). "In IR+/−/ApoE−/− we examined the effect of inhibiting Nox2 using genetic or pharmacological approaches on the development of atherosclerosis." (PMID 39401163, 2024). "Taken together, these findings confirm that suppressing LXN by genetic disruption can effectively improve atherosclerosis in ApoE-/- mice." (PMID 39424784, 2024).
atherosclerosis (continued). "Among other anti-atherogenic effects such as reduction of cardiac and vascular inflammation, ANGPTL4 reduces the phenotypic transition of SMCs into macrophage-like cells in the ApoE−/− mouse model of atherosclerosis." (PMID 38952543, 2024). "This study aims to elucidate the impact of nalmefene on atherosclerosis in apolipoprotein E knockout (ApoE KO) mice and peritoneal macrophages in vitro." (PMID 38560051, 2024). "This study aims to compare the therapeutic potential of liver-specific Angptl3 and Angptl4 silencing to attenuate hyperlipidemia and atherosclerosis development in APOE*3-Leiden.CETP mice, a well-established humanized model for lipoprotein metabolism." (PMID 39259836, 2024). "Chronic inflammatory response is another important pathological characteristic of atherosclerosis, we analyzed the expression levels of inflammatory cytokines in plasma and peritoneal macrophages from ApoE-/- mice, respectively." (PMID 39113703, 2024). "In the present study of female mice with atherosclerosis (ApoE-KO) at the beginning of reproductive senescence, the impact of the aging process on cardiac structure and function, hemodynamic parameters, and cardiovascular autonomic control were evaluated." (PMID 38570516, 2024). "In this study, ApoE-KO mice subjected to partial ligation and a high-fat diet at 1-week, 2-week, and 4-week intervals were used as an atherosclerosis model." (PMID 39337364, 2024). "A previous study showed that induction of endothelial cell (EC) ferroptosis promotes atherosclerosis in Apolipoprotein E−/− (ApoE−/−) mice." (PMID 38218337, 2024). "Our observations revealed elevated Piezo1 expression in plaque tissue and ECs of apoE−/− atherosclerotic mice with chronic atherosclerosis and DF‐induced atherosclerosis." (PMID 39450718, 2024). "In this study, we fed ApoE-/- mice with high fat diet to establish atherosclerosis model, and used Vevo2100 small animal ultrasound machine and ultra-high resolution MS-400 vascular probe to detect the relevant parameters of the artery." (PMID 38498570, 2024). "For instance, studies have shown that in APOE knockout mice, the increased expression of human aldose reductase accelerates atherosclerosis." (PMID 39272762, 2024). "These antibody constructs also reduced atherosclerotic plaque formation and C3 deposition in ApoE -/- mice effectively, presenting a promising strategy for treating atherosclerosis by targeting neoepitopes with complement inhibitors." (PMID 39735545, 2024). "The results suggest that E. faecium NCIMB11508 primarily inhibits atherosclerosis progression by managing inflammation in ApoE−/− mice." (PMID 39451408, 2024). "In this experiment, high WSS was primarily observed in ApoE-KO mice models with severe atherosclerosis through CFD simulation." (PMID 39337364, 2024). "The first evidence of the involvement of Tregs in pathogenesis of atherosclerosis was obtained in 2006, when it was demonstrated that ApoE−/− mice depleted with Tregs developed larger and more vulnerable atherosclerotic lesions." (PMID 39061983, 2024). "This study demonstrates that chronic systemic infection with P. gingivalis can accelerate the development of atherosclerotic lesions in ApoE-null mice, supporting the concept of a unified mechanism linking periodontal disease and atherosclerosis." (PMID 39610974, 2024). "Conversely, the overexpression of Ccl2 in ApoE−/− mice resulted in the acceleration of atherosclerosis." (PMID 38794213, 2024).
atherosclerosis (continued). "To investigate the influence of secondary atherosclerosis on arthritis mice, we treated the ApoE−/− mice with K/BxN serum and high fat diet (HFD), and subsequently assessed the phenotypes as well as immune profiles of K/BxN serum and HFD induced ApoE−/− mice." (PMID 39716053, 2024). "LXN knockout and LXN/ApoE double-knockout mice were generated to evaluate the functions of LXN in atherosclerosis." (PMID 39424784, 2024). "In our study, we used well-examined ApoE−/− mice to establish an atherosclerosis model by ligating the carotid artery, inducing low flow velocity and shear stress." (PMID 39175877, 2024). "The probiotic E. faecium NCIMB11508, according to our research, has a definitive capacity to prevent atherosclerosis progression by beneficially altering the SCFA composition in the gut microbiota of ApoE−/− mice." (PMID 39451408, 2024). "The ApoE(−/−) mouse has been a proven model for the spontaneous development of atherosclerosis in both male and female mice." (PMID 38659910, 2024). "Dietary intake of C20:5n-3 decreased the area of atherosclerosis lesions in apolipoprotein E-null (ApoE−/−) mice, one of the most widely used atherosclerosis models with lesions comparable to human lesions." (PMID 38410635, 2024). "The build-up of apoB48-rich remnant lipoproteins in the intima triggers an inflammatory response as shown in our results that the lesions of atherosclerosis of apoE KO rabbits contain more macrophages." (PMID 39087075, 2024). "ApoE-/- mice, when fed a Western diet, serve as the predominant murine models for studying atherosclerosis, with plaque formation serving as a pivotal indicator of atherosclerotic pathology." (PMID 39075604, 2024). "Additional studies have consistently shown that genetic deletion of NOX4 increases atherosclerosis in ApoE−/− mice." (PMID 38952543, 2024). "The main finding highlighted the role of gut microbiota in neoagaro-tetraose-mitigating atherosclerosis in HFHCD-fed ApoE−/− mice." (PMID 38794740, 2024). "The results from a rabbit model of atherosclerosis similarly indicate that inhibiting JAK/STAT signal transduction can reduce atherosclerosis in ApoE-/- mice." (PMID 38388385, 2024). "The IR+/−/ApoE−/−mice, however, developed significantly more atherosclerosis in the thoracoabdominal aorta and aortic sinus compared to their IR+/+/ApoE−/− littermates." (PMID 39401163, 2024). "Tang's research suggests that inhibiting JAK/STAT signal transduction can alleviate atherosclerosis in ApoE-/- mice." (PMID 38388385, 2024). "This study aims to examine the potential effects and mechanisms of Corilagin on atherosclerosis through the Olfr2 pathway, employing treatments on Ana-1 cells, primary mouse bone marrow-derived macrophages (BMDMs), and atherosclerotic models in ApoE−/− mice." (PMID 38803504, 2024). "In ApoE−/− mice, CKD induces a higher plaque burden, suggesting a higher risk of atherosclerosis in CKD conditions." (PMID 39040847, 2024). "This study aimed to investigate SDC-1 expression and its potential correlation with plaque vulnerability in ApoE−/− atherosclerosis mouse model." (PMID 39175877, 2024). "The same group detected a dose-driven decrease in atherosclerosis in Tie1-attenuated ApoE−/− mice, supporting the concept that Tie1 is a crucial controller of the endothelial reaction to perturbed shear stress." (PMID 39507419, 2024). "The LT receptor antagonist decreased atherosclerosis in ApoE-knockout mice and reduced the infarct size in a murine ischemia-reperfusion model." (PMID 38921429, 2024). "Similarly, biglycan has been shown to be protective in a mouse model of atherosclerosis, where APOE-deficient mice, also deficient in biglycan, displayed enhanced circulating thrombin levels, elevated platelet activation and increased adhesion in vivo compared to control APOE knockouts." (PMID 38256024, 2024).